TNF (tumor necrosis factor)
Diseases named in the same sentence as TNF in open-access papers (continued):
Sharing a sentence is not in itself a finding about the gene and the disease.
rheumatoid arthritis (continued). "Specifically, supplementing the diet with lyophilized TC powder prevented age-related bone loss in female C57BL/6 mice and mitigated bone loss in a tumor necrosis factor (TNF)-overexpressing transgenic model of rheumatoid arthritis." (PMID 40944216, 2025). "Tumor necrosis factor-α (TNF-α) is chosen in our study due to its implicated role in inflammatory and autoimmune diseases such as kidney injury, psoriasis, and rheumatoid arthritis." (PMID 40278482, 2025). "Rheumatoid arthritis (RA), for example, is an autoimmune condition associated with increased peripheral inflammation and inflammatory markers such as the cytokine TNF-a, which is also upregulated in the brains of AD patients." (PMID 39860337, 2025). "Recent findings from East Asian populations have also identified associations between KTCN and pathways related to rheumatoid arthritis, highlighting the activation of immune cells and the release of inflammatory cytokines such as TNF-α, IL-1, and IL-6." (PMID 40426861, 2025). "A third study in patients with rheumatoid arthritis reported that the same allele influenced the response to TNF-α inhibitors, supporting the notion of altered receptor signaling dynamics." (PMID 40862731, 2025). "Gene ontology analysis demonstrated differential expression of genes related to inflammation including IL-17 pathway and other inflammatory signaling pathways implicated in rheumatoid arthritis and TNF signaling pathways." (PMID 41031886, 2025). "In patients with rheumatoid arthritis, tofacitinib has been associated with a higher risk of lung cancer and lymphoma compared to TNF inhibitors." (PMID 40952332, 2025). "In the context of autoimmune diseases, aberrant ADAM17 activity has been linked to elevated TNF-α levels and chronic inflammation in conditions such as rheumatoid arthritis (RA), systemic lupus erythematosus (SLE), psoriasis, and Crohn’s disease." (PMID 41050403, 2025). "Other comorbid disorders include type 1 diabetes, associated with IL-17 and IL-6 dysregulation, and rheumatoid arthritis, typically characterized by TNF-α and IL-1β elevation." (PMID 40430113, 2025). "Beyond diabetes, systemic inflammatory diseases such as rheumatoid arthritis share overlapping cytokine profiles (e.g., elevated IL-6 and TNF-α) and are associated with increased periodontal and cardiovascular risk." (PMID 41007869, 2025). "A subsequent study revealed that compared to those treated with TNF-α inhibitors, patients on baricitinib for rheumatoid arthritis had an elevated risk of encountering adverse cardiovascular events and venous thromboembolism." (PMID 40860887, 2025). "Since TNF-α inhibitors can lessen inflammation and prevent systemic bone loss, they are frequently used in clinical practice as the first-line therapy for rheumatoid arthritis." (PMID 40873591, 2025). "The significance of TNFα in bone loss is demonstrated by the efficacy of anti-TNFα therapies, which can substantially decrease inflammation and inhibit joint damage in rheumatoid arthritis treatment." (PMID 40688496, 2025). "Tumor necrosis factor–α (TNFα) is a proinflammatory cytokine that plays an important role in bone loss in rheumatoid arthritis." (PMID 40688496, 2025). "KEGG enrichment analysis identified the top-ranked biological processes “Cytokine-cytokine receptor interaction”, “Rheumatoid arthritis”,” TNF signaling pathway”, all of which are linked to inflammatory functional signatures." (PMID 38750493, 2024). "We review the abnormal bone turnover that is the basis of idiopathic inflammatory or rheumatoid arthritis and bone loss, with emphasis on Tumor Necrosis Factor-alpha (TNFα)-related mechanisms." (PMID 39082340, 2024). "For example, in rheumatoid arthritis, TNF-α and IL-6 are the main players causing inflammation and, consequently, joint destruction." (PMID 39062908, 2024).
rheumatoid arthritis (continued). "Prevotella has also been linked to inflammatory conditions, including rheumatoid arthritis, where it maintains an inflammatory state by stimulating pro-inflammatory cytokines (TNF-α and IFN-γ) produced by CD8+ T cells and TH17." (PMID 39203576, 2024). "The role of TNF-α in urinary tract infections is of great relevance, in this respect, it has been observed in patients with rheumatoid arthritis treated with specific TNF-α inhibitors that the risk of suffering UTIs is notably increased." (PMID 38892345, 2024). "TNF-α is also considered to be a pro-atherogenic cytokine and patients with rheumatoid arthritis treated with anti-TNF-therapies have been shown to have reduced risk of cardiovascular events." (PMID 39091640, 2024). "Inflammatory conditions such as rheumatoid arthritis (RA), psoriasis, and inflammatory bowel disease, where TNF plays a significant role, are associated with a higher likelihood of developing AD." (PMID 38852117, 2024). "Our study also reports that Vigeo inhibited arthritis symptoms, including bone loss and serum levels of TNF-α, IL-6, and IL-1β, in a mouse model of collagen-induced arthritis/rheumatoid arthritis." (PMID 39203823, 2024). "This cohort study assesses the association of tumor necrosis factor inhibitors, non–tumor necrosis factor inhibitor drugs, and Janus kinase inhibitors with incident cancer risk among patients with rheumatoid arthritis." (PMID 39565623, 2024). "Psoriasis is related to other pathologies such as rheumatoid arthritis, and in this pathology, this SNP has been found to be associated with a lower short-term response to anti-TNF therapy." (PMID 39857589, 2024). "Macrophages and macrophage-derived cytokines (TNFα, IL-6 and GM-CSF) have a major pathogenic role in rheumatoid arthritis (RA)." (PMID 38528207, 2024). "Some studies have shown an increased risk of lymphoma in rheumatoid arthritis patients with TNF-α inhibition." (PMID 39046819, 2024). "Inflammation-induced upregulation of systemic TNF levels (along with IL-1beta levels) has also been suggested to augment the risk for periodontitis in patients suffering from rheumatoid arthritis." (PMID 39253090, 2024). "TNF-α blockade in autoimmune diseases like rheumatoid arthritis is associated with the unmasking of a type I IFN signature and the development of drug-induced lupus." (PMID 39688922, 2024). "Levels of n-3 PUFA in plasma were associated with clinical improvements in patients with rheumatoid arthritis to anti-TNF therapy by suppressing Th17 differentiation." (PMID 38892051, 2024). "The A allele is associated with increased production of TNF-alpha and is linked to various inflammatory diseases such as rheumatoid arthritis, inflammatory bowel disease and asthma." (PMID 38999258, 2024). "Many of the cytokines dysregulated in periodontitis, such as IL-6, TNF-α, and IL-17A, play pathogenic roles in conditions like cardiovascular disease, rheumatoid arthritis, diabetes, stress, and certain cancers." (PMID 38891939, 2024). "As seen in conditions like rheumatoid arthritis, chronic exposure to TNF-α is associated with reduced bone formation and increased bone resorption in humans." (PMID 39767573, 2024). "For example, tumor necrosis factor α (TNF-α) is implicated in diseases such as rheumatoid arthritis and Crohn’s disease." (PMID 38760355, 2024). "TNF-α is a proinflammatory cytokine that is associated with many inflammatory diseases, such as rheumatoid arthritis, psoriasis and Crohn's disease, and thus anti-TNF-based therapies have been developed to treat these conditions." (PMID 39091640, 2024). "A natural substance that reduced CRP and proinflammatory, IL6 and TNFα were used as complementary therapy for managing rheumatoid arthritis, a chronic inflammatory condition associated with an increased risk of hypertension." (PMID 39558500, 2024).
rheumatoid arthritis (continued). "TNF-α and IL-6 are also implicated as pathogenic factors in immune-related bone disorders, including rheumatoid arthritis and postmenopausal osteoporosis, further highlighting their pathogenic potential to bone." (PMID 39596106, 2024). "RNA-seq data analyses using a protein–protein interaction network showed downregulation of the TNF signaling pathway- and rheumatoid arthritis-associated genes in FP2-cultured cells versus control cells." (PMID 37777063, 2024). "Dysregulation of the TNF signaling pathway has been implicated in the pathogenesis of a variety of diseases, including rheumatoid arthritis and inflammatory bowel disease." (PMID 38194722, 2024). "The association of inflammatory CNS events with TNF inhibitor exposure was observed in patients with rheumatoid arthritis." (PMID 39078559, 2024). "The Oral Rheumatoid Arthritis Trial Surveillance demonstrated an increased cancer risk among patients with rheumatoid arthritis (RA) taking tofacitinib compared with those taking tumor necrosis factor inhibitors (TNFis)." (PMID 39565623, 2024). "A review of the novel sites using the EWAS Catalog showed previous associations with Crohn’s disease, rheumatoid arthritis, systemic lupus erythematosus, and TNF-α for NLRC5 (Nod-like receptor family CARD domain containing 5; cg16411857)." (PMID 38571307, 2024). "For instance, the presence of rheumatoid arthritis has been shown to increase the risk for periodontitis occurrence and this effect correlated with increased levels of IL-1beta and TNF in the gingival crevicular fluid of patients suffering from both disorders." (PMID 39253090, 2024). "TNF-α inhibitors have been shown to be associated with a lower risk of dementia in patients with rheumatoid arthritis and animal studies, but there are concerns of adverse events and the blocking physiological role of TNF-α through TNFR2." (PMID 37371414, 2023). "We found that medium-term humoral immunity was attenuated in anti-neutrophil cytoplasmic antibody-associated vasculitis and rheumatoid arthritis (RA) patients treated with glucocorticoids, tumor necrosis factor-α inhibitors (TNFis), or abatacept." (PMID 36569794, 2023). "Other studies conducted on patients suffering from rheumatoid arthritis or ankylosing spondylitis suggest an association between response to anti-TNF-α agents and the IL-17F SNP." (PMID 37239484, 2023). "Rheumatoid arthritis (RA), a bone disorder that affects both bones and joints, links osteoporosis to bone loss and inflammation enhanced by increased levels of TNF-α, IL-1β, and metalloproteinases." (PMID 38067111, 2023). "The Spanish register (BIOBADASER) found that anti-TNF therapy is associated with higher susceptibility to severe infections in rheumatoid arthritis (RA) patients in particular during the first 6 months of treatment." (PMID 37189785, 2023). "Functional enrichment uncovered that these genes were implicated in TNF signaling pathway, IL-17 signaling pathway and rheumatoid arthritis pathways." (PMID 36681837, 2023). "Increased level of α7 nAChR correlated with excessive inflammation and synthesis of tumor necrosis factor and caused morbidity and mortality in diverse human diseases including endotoxemia, sepsis, rheumatoid arthritis, and inflammatory bowel disease." (PMID 37013615, 2023). "The TNF −238A allele (rs361525) has also been implicated in a number of autoimmune diseases including rheumatoid arthritis, ankylosing spondylitis, systemic lupus erythematosus, juvenile idiopathic arthritis, Graves’ disease, and type I diabetes mellitus." (PMID 36979841, 2023). "Sustained increases in TNF are associated with chronic inflammation and tissue damage in inflammatory bowel disease and rheumatoid arthritis, and with ROS-mediated tissue damage in Mm infections in zebrafish." (PMID 37200402, 2023). "Rheumatoid arthritis, in turn, has been reported to be caused by IL-6 and TNF-α secreted from M1 macrophages." (PMID 36768216, 2023).
rheumatoid arthritis (continued). "Since TNF-α also plays a role in the development of autoimmune diseases, it is associated with the developmental pathophysiology of diseases such as rheumatoid arthritis (RA), ankylosing spondylitis (AS), and Crohn's disease." (PMID 38223592, 2023). "Meanwhile, IL-17 signaling, rheumatoid arthritis, and TNF signaling KEGG pathways were all linked to the cytokine–cytokine receptor interaction pathway through expression of CXCL2." (PMID 35881197, 2023). "An abnormal production of TNF-α is associated with several chronic, immunoinflammatory diseases, such as rheumatoid arthritis (RA), inflammatory bowel disease (IBD), psoriasis (PS), psoriatic arthritis (PsA) and autoimmune uveitis." (PMID 36836166, 2023). "As an agonist, both the mRNA encoding TNF-α and the translated protein have short half-lives so chronic effects such as rheumatoid arthritis or atherosclerosis require chronic gene expression." (PMID 37534280, 2023). "TNF-α is positively associated with a variety of inflammatory diseases, such as rheumatoid arthritis, acute liver injury, and lung cancer." (PMID 37174310, 2023). "Dysregulated TNF-α signaling has been associated with multiple inflammatory and autoimmune diseases, including rheumatoid arthritis, psoriasis, and inflammatory bowel disease (IBD)." (PMID 37373082, 2023). "Anti-TNF-α therapy in rheumatoid arthritis patients reduces the risk of all cardiovascular events (myocardial infarction, cerebrovascular accident, congestive heart failure)." (PMID 37887854, 2023). "Most of these cases were reported in patients with rheumatoid arthritis, most probably because of the high incidence of the disease and the associated frequent use of TNF-α blocking agents for this indication." (PMID 37512971, 2023). "Studies also evaluated the effect of Infliximab on rheumatoid arthritis patients with co‐existing periodontitis and noticed that they exhibited decreased periodontal attachment loss, and had lower periodontal indices and TNF‐α gingival crevicular fluid levels." (PMID 34626163, 2022). "A multivariate model of rheumatoid arthritis revealed a > 2-fold risk of severe COVID- 19+ve, or death, for patients taking TNF inhibitors plus prednisone, compared with those on conventional disease modifying drugs or non-rheumatoid arthritis controls." (PMID 36440212, 2022). "Retrospective studies showed that TNF inhibition medications decreased the risk of colorectal cancer in patients with inflammatory bowel disease or rheumatoid arthritis." (PMID 36618924, 2022). "TNF, also known as TNF-α, is a well-known proinflammatory cytokine that is released by white blood cells and can induce systemic or cellular inflammation, causing rheumatoid arthritis." (PMID 35662946, 2022). "HIV/AIDS and the treatment of patients suffering from autoimmune inflammatory diseases, such as rheumatoid arthritis or Crohn`s disease, with tumor necrosis factor (TNF) antagonists are associated with an increased risk of reactivating TB (61, –, 64)." (PMID 34871095, 2022). "TNF-α inhibitors reduce the risk of joint damage, improve physical function, and consequently, the quality of life of patients with rheumatoid arthritis, an autoimmune disease that causes chronic pain and joint pain, including TMJ." (PMID 35239943, 2022). "IFN-γ and TNF-α are associated with many inflammatory diseases, including rheumatoid arthritis and systemic lupus erythematosus." (PMID 35990653, 2022). "Haplotypes defined by amino acids at HLA-DRB1 positions 11, 71 and 74 associated with susceptibility to rheumatoid arthritis (RA) are associated with radiological outcome, anti-TNF response and all cause-mortality in RA." (PMID 35468805, 2022). "Any substance that blocks the production of IL-6 and TNF-α causes a significant revolution in the management of rheumatoid arthritis." (PMID 36353479, 2022). "Tumor necrosis factor (TNF) inhibitors increase the risk of tuberculosis (TB) in patients with rheumatoid arthritis (RA)." (PMID 35761359, 2022).
rheumatoid arthritis (continued). "Numerous studies in adults have associated vitD sufficiency with a reduction in TNF-associated inflammation in asthma, rheumatoid arthritis, heart disease, inflammatory bowel disease, psoriasis, and development of metabolic syndrome." (PMID 35334923, 2022). "Systemic inflammation and related inflammatory markers (e.g., tumor necrosis factor) are associated with increased risk of several circulatory system diseases, inflammatory bowel disease, and rheumatoid arthritis." (PMID 35816897, 2022). "The iNOS and COX-2 expressions are controlled by pro-inflammatory cytokines, such as TNF-α, IL-1β, and IL-6, which are implicated in numerous autoimmune and inflammatory diseases, including rheumatoid arthritis, uveitis, and sclerosis." (PMID 35877707, 2022). "Cases of anti-TNF associated demyelination have been described in patients with Crohn’s disease, psoriasis, rheumatoid arthritis and ankylosing spondylitis potentially hinting to a rare but relevant safety signal." (PMID 35694196, 2022). "In rheumatoid arthritis, a previous report found that the combined inhibition of IL-17 and TNF-α was effective in blocking tissue destruction associated with arthritis." (PMID 35844613, 2022). "In our series, as well as in the literature, rheumatoid arthritis and systemic lupus erythematosus are the most common autoimmune diseases associated with toxoplasmosis, and antimetabolites, anti-TNF-α and corticosteroids were involved in most cases." (PMID 35939518, 2022). "PAD2 and PAD4 are present in the rheumatoid joint, have genetic variants associated with rheumatoid arthritis risk, and are required for full arthritis severity in TNF-induced arthritis, a murine model of innate inflammation in arthritis." (PMID 35083342, 2022). "Tumor necrosis factor (TNF) inhibitors use in patients with rheumatoid arthritis (RA) has raised safety concerns about cancer risk, but study results remain controversial." (PMID 35945635, 2022). "The inflammatory cytokine TNF-α has a role in both innate and adaptive immunity, underlying the efficacy of TNF inhibitors in patients with autoimmune conditions like rheumatoid arthritis (RA) and autoinflammatory conditions like Deficiency of ADA2 (DADA2)." (PMID 35281022, 2022). "The treatment of ankylosing spondylitis and rheumatoid arthritis with TNF-α inhibitors was associated with a concurrent decrease in the DKK1 serum levels." (PMID 35393522, 2022). "From 2015 to 2017, IFN-gamma, recruitment, lipopolysaccharide, tumor necrosis factor-alpha, fatty acid oxidation, rheumatoid arthritis, hypercholesterolemia, in vivo, and tumor-associated macrophage were critical research directions." (PMID 35795675, 2022). "Remarkably, the abnormality of TNF-α level and signaling cause the development of disease, such as rheumatoid arthritis, psoriasis, Crohn's disease, atherosclerosis, and cancer." (PMID 36187334, 2022). "TNF-α inhibitors have been used to treat rheumatoid arthritis, TNF 1-associated fever, juvenile idiopathic arthritis, ulcerative colitis, and Crohn’s disease in children for more than a decade." (PMID 36232430, 2022). "Gene sets related to diuretics, metformin, fenofibrate, and TNF inhibitor used for rheumatoid arthritis showed association with tinnitus." (PMID 36581688, 2022). "Bone destruction is accelerated in inflammatory diseases associated with increased TNF-α production, including ankylosing spondylitis, inflammatory bowel disease, periodontitis and rheumatoid arthritis." (PMID 33861790, 2021). "TNFα has been implicated to play a major role in the pathogenesis of inflammation-associated diseases like asthma, rheumatoid arthritis, and inflammatory bowel disease." (PMID 34093519, 2021). "Osteoclastic bone destruction observed in autoimmune diseases, such as rheumatoid arthritis, is caused by inflammatory cytokines, including IL-1, IL-6, TNF-α, and IL-17, which increase RANKL expression in synovial fibroblasts." (PMID 33633362, 2021).